CRP (C-reactive protein)
Diseases named in the same sentence as CRP in open-access papers (continued):
Sharing a sentence is not in itself a finding about the gene and the disease.
pneumonia (continued). "Thus, the aim of this study was to investigate how viral pathogens detected in the nasopharynx and conventional inflammatory markers (WBC and CRP) correlate to signs, symptoms and prognosis of pneumonia among the age group of 65 years and over." (PMID 30991957, 2019). "Similarly, median CRP levels of moderate and severe pneumonia increased by − 1.5 and 9.5%, respectively, compared with those of mild pneumonia in elderly patients." (PMID 30616612, 2019). "In summary, we concluded that patients present with pneumonia and pleural effusion signs on the chest x-ray and the combination of the serum CRP with the serum calprotectin constitutes a more highly sensitive and specific assay for the differential diagnosis of UPPE and CPPE/empyema." (PMID 31215423, 2019). "The optimum CRP threshold for differentiating definite bacterial from presumed viral and other pneumonia had only moderate predictive value which could limit its use as a sole criterion for antibiotic decision-making in clinical settings." (PMID 30940126, 2019). "The AUC for CRP was 0.82 (95% CI: 0.73, 0.91) for discriminating definite bacterial from presumed viral pneumonia and 0.81 (95% CI: 0.72, 0.89) for discriminating definite bacterial from presumed viral plus other pneumonias." (PMID 30940126, 2019). "Six different laboratory tests (white blood cell count (WBC), erythrocyte sedimentation rate (ESR), C-reactive protein (CRP), procalcitonin (PCT), lipopolysaccharide binding protein (LBP) and fibrinogen were used to examine the diagnostic value of radiographic pneumonia." (PMID 31110214, 2019). "In settings with a higher prevalence of pneumonia, the presence of chest retractions, a saturation <94%, and additional tests such as CRP and WBC may further support an accurate diagnosis of pneumonia." (PMID 30367067, 2018). "On the other hand, children with no clinical signs of pneumonia and low CRP results were at a lower risk for pneumonia." (PMID 29988379, 2018). "The measurement of CRP with a POCT has been proved accurate and can increase diagnostic certainty if combined with clinical examination—especially for identifying patients at high risk of pneumonia." (PMID 29554972, 2018). "Hazard ratio of 1.94 for having pneumonia in ICS group (p=0.008); unchanged when analysis restricted only to patients with CXR.Higher risk in those with baseline severe dyspnoea and baseline raised CRP." (PMID 34541493, 2018). "Children with pneumonia had significantly lower SatO2 (p 0.001) and higher CRP levels (p 0.023) and they required oxygen supplementation to maintain SatO2 ≥ 92% in a higher percentage (p < 0.0001) and for longer time (p < 0.0001) compared to the patients with simple bronchiolitis." (PMID 30526548, 2018). "Additionally, all patients with low albumin and high CRP levels developed pneumonia initially or subsequently, even with the administration of effective antimicrobials, and subsequently died." (PMID 28938875, 2017). "Furthermore, more children with RSV and co-detection were born premature and had ≥ 1 chronic disease; they also developed a higher peak temperature, higher peak CRP levels, more often had pneumonia and less often had bronchiolitis." (PMID 28095451, 2017). "In conclusion, we exclude that TUS could reliably replace CXR, and we confirm that the assessment of physical signs, CXR, and biomarkers such as procalcitonin and CRP, remain the pillars for the diagnosis of pneumonia." (PMID 28859628, 2017). "Pneumonia, a higher rate of leukocytes and C-reactive protein were more frequent in HAdV or HBoV." (PMID 28301570, 2017). "Within the UK, POC CRP has been recommended in the NICE pneumonia guidelines." (PMID 26940107, 2016). "CRP was accurate in identifying pneumonia (area under the curve 0.84, 95% CI 0.82–0.87)." (PMID 27610265, 2016). "A prospective study was therefore conducted in a large and unselected population with the goal of clarifying whether serum CRP could identify patients with pneumonia." (PMID 27610265, 2016).
pneumonia (continued). "Also, the median initial serum WBC and CRP were significantly higher in the ADHF with pneumonia group than in the ADHF group (10,470 cells/mL vs. 8,200 cells/mL, p<0.001 and 6.10 mg/dL vs. 0.56 mg/dL, p<0.001)." (PMID 27682424, 2016). "Recent guidelines and review studies have suggested that serum C-reactive protein (CRP) may be helpful in distinguishing pneumonia from other acute respiratory illnesses." (PMID 27610265, 2016). "Indeed, serum CRP levels above 200 mg/L or below 75 mg/L make the diagnosis of pneumonia likely or unlikely, respectively." (PMID 27610265, 2016). "In addition, our study shows that for each 10 mg/L increase in CRP, the likelihood (odds) of pneumonia increases by 30%." (PMID 26937636, 2016). "After adjustment for age and sex, median levels of hs-CRP were significantly higher in patients with pneumonia (116 mg/L, IQR 46.5–179.0, vs 22.5 mg/dl, IQR 6.9–84.4, p < 0.0001), while procalcitonin median levels were not (0.22 ng/ml IQR 0.12–0.87, vs 0.15 ng/ml, IQR 0.10–0.35, p = 0.08)." (PMID 26772604, 2016). "Serum CRP is a sensitive marker of pneumonia, and its measurement is considered common practice." (PMID 27682424, 2016). "Serum CRP may be a useful addition for diagnosing pneumonia in hospitalized patients with acute respiratory symptoms." (PMID 27610265, 2016). "If IMCI in combination with CRP and/or other biomarkers could play a similar role by reliably confirming or excluding bacterial infections like pneumonia needs to be further studied." (PMID 26821179, 2016). "Compared to children with normal x-ray, children with end-point pneumonia had significantly higher C-reactive protein, procalcitonin and Chitinase 3-like-1, while those with other infiltrates had elevated procalcitonin and von Willebrand Factor and decreased soluble Tie-2 and endoglin." (PMID 26366571, 2015). "The CRP level used as a follow-up parameter for pneumonia in addition to the clinical parameters." (PMID 26430738, 2015). "Finally, the overall mortality in the study cohort was a limiting factor that precluded modelling the influence of SIRS criteria, CRP trends, or pneumonia on mortality." (PMID 25484622, 2014). "Additionally, recent studies showed that obese patients with pneumonia had lower pneumonia severity index scores and plasma levels of C-reactive protein." (PMID 24722122, 2014). "In this study, we found no marked increase in CRP, and no cases of bacteremia and pneumonia, caused by probiotics in the patients." (PMID 24990477, 2014). "The cutoff levels of plasma SDF-1 and CRP were selected as 2208 ng/mL and 15.3 mg/L, respectively, according to operating characteristics curve (ROC) analysis to distinguish the patients with pneumonia from the control groups." (PMID 25371597, 2014). "Based on atypical bilateral infiltrations in the X-ray and highly elevated c-reactive protein (CRP), she was hospitalised with the diagnosis of pneumonia and treated with antibiotics while everolimus was paused; the last octreotide LAR injection was given 2 weeks prior to this." (PMID 25520848, 2014). "According to these guidelines, CRP testing can be done in patients with suspected pneumonia." (PMID 24886066, 2014). "Another cohort study from Brazil in 331 patients with a rate of 16% for postoperative pneumonia comes to the conclusion that preoperative level of highly sensitive C-reactive protein (CRP) >3 mg/l is an independent predictor for postoperative respiratory infection." (PMID 24321282, 2013). "Although detection of elevated CRP levels is sensitive for severe acute pancreatitis it is not specific for the disease, and other causes of inflammation such as cholangitis and pneumonia need to be ruled out before severity assessment by measurement of CRP." (PMID 24204087, 2013). "Interestingly, the presence and speed of CRP decrease also have been found to correlate with prognosis in ICU patients with severe pneumonia." (PMID 23787145, 2013).
pneumonia (continued). "However, CRP has been shown to activate complement pathways and lead to opsonization of bacteria such as Streptococcus pneumonia, suggesting that CRP should perhaps be protective against pneumonia." (PMID 23457535, 2013). "During a pneumonia episode a CRP ≥40 mg/L was associated with PEP on CXR (p<0.001) but not with OI (p = 0.004)." (PMID 23320118, 2013). "In patients with cough, feeling of increased body temperature, and a CRP level below 50 μg/ml, but without dyspnea and daily subjective feeling of increased body temperature since the onset of cough, pneumonia can be ruled out safely as the underlying illness." (PMID 23245504, 2012). "Besides, we also found that PlGF levels were more sensitive in the prediction the pneumonia (or airway inflammation) than CRP." (PMID 21962211, 2011). "In addition, the severe pneumonia patients who received corticosteroids (17 cases) had the highest leukocyte counts and CRP levels, and the lowest lymphocyte differentials (11 800 ± 3600/mm3, 3.0 ± 3.1 mg/dL, and 8.8 ± 6.3%, respectively)." (PMID 21864391, 2011). "When we divided and evaluated these school-aged children into three groups according to severity of pneumonia, as previously stated, the patients with more severe pulmonary lesions showed higher CRP levels (p = 0.02) and a higher proportion of seroconverters (p = 0.001, ANOVA test)." (PMID 20604923, 2010). "As we have shown, improvement of epidemiological definitions with PCT and/or CRP may be limited in malaria-endemic countries, as malaria parasites increase levels of both markers independently of the pathogen responsible of pneumonia." (PMID 20976241, 2010). "How malaria parasitemia and other prevalent co-morbidities may alter PCT and CRP levels in presence of pneumonia remains to be explored." (PMID 20976241, 2010). "In 106 military conscripts who had pneumonia, CRP, with a cut-off value of 85 mg/L, could differentiate pneumococcal pneumonia from viral and mycoplasmal pneumonia." (PMID 20011658, 2009). "However, the advantage of CRP is that CRP levels can be used for the follow-up of pneumonia as well as to evaluate patient management and response to antibiotic therapy." (PMID 20011658, 2009). "In contrast, a study by Cheung found that CRP was a better discriminator of pneumonia than PCT." (PMID 19675669, 2009). "- Pneumonia: Pulmonary infection with evidence of increased infection parameters (CRP > 2 mg/dl and/or leukocytes > 10 000/ml) which are unlikely to be caused by a different pathologic process and evidence of pulmonary infiltrates on chest x-ray, requiring antibiotic therapy." (PMID 19825186, 2009). "A C-reactive protein (CRP) point of care test may help GPs to better guide antibiotic treatment by ruling out pneumonia in cases of low test results." (PMID 17394651, 2007). "CRP was put forward as a useful marker for predicting disease severity in patients with pneumonia." (PMID 16805922, 2006). "The patient with pneumonia had a CRP value of 8 mg dl-1 at that time." (PMID 16277717, 2005). "Whereas vaccine efficacy was not significant for CXR-confirmed pneumonia (9%; p = 0.38), vaccine efficacy was significant when measured against CXR-confirmed pneumonia in conjunction with a CRP level of 120 mg/l or more (35%; p = 0.03) or a procalcitonin level of 5 ng/ml or more (33%; p = 0.04)." (PMID 15736995, 2005). "Our data suggest that the outcome measure of CXR-confirmed pneumonia together with elevated CRP and procalcitonin levels may be more accurate as a surrogate of pneumococcal pneumonia than CXRs on their own." (PMID 15736995, 2005). "The sensitivity of CXR-confirmed pneumonia plus CRP ≥120 mg/l plus procalcitonin ≥5 ng/ml in detecting vaccine efficacy against pneumococcal pneumonia was analysed by comparing the VAR per 100,000 child years to that observed using an outcome of bacteremic pneumococcal pneumonia." (PMID 15736995, 2005).
pneumonia (continued). "Beyond CRP, immune cell-derived markers such as the NLR have been associated with PPC risk in lung-cancer surgical cohorts, while infection-oriented biomarkers such as PCT, alone or combined with cytokine dynamics, can aid early identification of postoperative pneumonia in selected settings." (PMID 41598637, 2026). "Additionally, CRP levels in pneumonia patients are abnormally elevated." (PMID 39926661, 2025). "In this case, CRP may help to discern pneumonia and COPD from NET." (PMID 39703761, 2025). "Besides the higher CRP, pneumonia and COPD were characterized by the higher serum proGRP." (PMID 39703761, 2025). "However, while serum CRP values in parapneumonic infection exceed that of uncomplicated pneumonia, the rate of decline may be slower, limiting direct comparisons." (PMID 41523477, 2025). "As in other viral infections, an increase in CRP is also possible in measles; it is especially noted that its value begins to rise in parallel with the appearance of the rash and that it increases significantly with developed complications such as pneumonia and encephalitis." (PMID 39064460, 2024). "In contrast, it was expected that the levels of CRP and the htCRNT values for the Delta-derived variant would be higher in the vaccinated patients with pneumonia than in the unvaccinated patients with pneumonia; however, these differences were also not statistically significant (P>0.05)." (PMID 38694512, 2024). "Furthermore, the Mortality group exhibited significantly higher levels of white blood cells, neutrophils, D-dimer, creatinine, and C-reactive protein in the blood, as well as a higher incidence of pneumonia, while the platelet count was significantly lower compared to the Survival group." (PMID 38200490, 2024). "Pneumonia may use CRP as a clinical measure instead of TNF-alpha or IL-6." (PMID 39727640, 2024). "CRP showed a significant increase in patients with post-COVID-19 pneumonia (9.57 ± 9.02 mg/L vs. 4.85 ± 2.80 mg/L, p = 0.046) as well as interleukin-6 (IL-6) levels that were substantially elevated in the pneumonia group (6.75 ± 6.59 pg/mL vs. 1.43 ± 1.77 pg/mL, p < 0.001)." (PMID 39202577, 2024). "Additionally, higher levels of CRP and lower levels of oxygen saturation could predict the development of pneumonia in these patients." (PMID 38475703, 2024). "This MR study suggested a potential role of increasing genus Roseburia and family Bifidobacteriaceae abundance, as well as stearidonate (18:4n3), in mitigating inflammation or infectious risks, which could reduce CRP, SAA1, or GlycA levels, pneumonia, or UTI risk." (PMID 38585702, 2024). "Lastly, although our study identify a relationship between CRP and the progression of CR-AB pneumonia to associated bacteremia, we could not analyze the impact of changes in indicators over time or disease evolution, etc. on the final outcome." (PMID 37768395, 2023). "Our study aimed to establish if baseline levels of complete blood cell count-derived biomarkers and CRP, measured before any treatment which can interfere with their values, could serve as a predictor of development of pneumonia and the need for hospitalization requiring oxygen therapy." (PMID 37570378, 2023). "Some clinicopathological features of SCAP patients, such as CRP, ALB, NLR, and NGAL, were reported to possess significant diagnostic or prognostic value in CAP or other types of pneumonia, but their significance was insignificant in the present study, which might result from the small sample size." (PMID 37291525, 2023). "Moreover, CRP levels among patients with mild/moderate pneumonia and those with diffuse bilateral interstitial and airspace opacities were significantly higher at T0 compared to T1 (Z = 2.934; p = 0.0033 and Z = 2.903; p = 0.0037, respectively) (data not shown)." (PMID 37228441, 2023).
pneumonia (continued). "In addition to observing multiple clinical variables associated with pneumonia, we identified 3 baseline serum protein immunoassay measures (GDF-15, MMP-8 and CRP), after adjusting for clinical variables, that were associated with pneumonia events up to 10 years prior to the pneumonia diagnosis." (PMID 38105941, 2023). "However, in our case, because the chest X‐ray and non‐contrast chest CT showed shadows in the upper lobe of the right lung on admission, the inflammatory signs such as fever, increased white blood cell count, and elevated CRP were initially thought to be due to pneumonia." (PMID 36408084, 2022). "In our data we did not differentiate between bacterial and viral pneumonia, but we similarly observed that higher CRP tends to be associated with pneumonia, but that lower CRP might not exclude it." (PMID 36333682, 2022). "The analysis showed an association between pneumonia and heart failure on NYHA III and IV scale (OR = 4.56, p < 0.001), COPD (OR = 2.66, p < 0.001), extracardiac arteriopathy (OR = 3.06, p < 0.001), NIHHS scale at discharge (OR = 1.15, p < 0.001), and CRP/HGB ratio (OR = 1.17, p < 0.001)." (PMID 36430028, 2022). "In this study of 805 Ugandan children with pneumonia, sTREM-1 measured at hospital presentation was a significantly better predictor of children at risk of 48-hour and in-hospital death than respiratory rate, peripheral oxygen saturation, lactate, procalcitonin (PCT), or C-reactive protein (CRP)." (PMID 35830474, 2022). "CRP is a well-established biomarker of inflammation but has been considered as a non-specific marker in the pneumonia diagnosis, although it might have some values in defining pneumonia severity." (PMID 35307030, 2022). "Compared with neither crackles nor wheeze, any wheeze was associated with lower CRP (<40 mg/L) on conventional auscultation (aOR=0.50, 95% CI 0.27 to 0.92) and was inversely associated with very severe pneumonia status on digital auscultation (aOR=0.67, 95% CI 0.46 to 0.97)." (PMID 35577452, 2022). "The mean age and median C-reactive protein level were higher in group B than in group A. All patients in group A and one-third of patients in group B had normal initial chest radiographs; 15.8% and 48.1% of patients in groups A and B, respectively, had pneumonia during hospitalization." (PMID 34757529, 2021). "Notably, pneumonia cases where RV was the only respiratory virus detected in the nasopharyngeal/oropharyngeal sample in our study had higher viral loads, elevated CRP levels, and higher case fatality ratio compared with cases with RV and other viral co-infections after adjusting for site and age." (PMID 34198998, 2021). "CRP may also serve as a possible biomarker for infection and pneumonia in geriatric patients." (PMID 33816541, 2021). "In detail the strength of the association, measured by the value of OR concerns pneumonia, pneumonia bilateral distribution, negative outcome, above normal range values of CRP, LDH, aspartate aminotransferase (AST), hypocalcemia, and with below normal range values of lymphocytes and sodium." (PMID 33960733, 2021). "The main novelty of our report is the finding that using easily accessible information (age, C-reactive protein level, presence of bilateral infiltrate, and abdominal pain), we could separate people with SARS-CoV-2-associated pneumonia from those with other aetiologies." (PMID 33174170, 2021). "Thus, a CRP more than 20 mg/L might have some utility in predicting severe pneumonia in our and similar settings." (PMID 32605136, 2020). "This study has a pragmatic approach, notably not to evaluate the actual accuracy of the diagnostics of pneumonia but to illuminate the diagnostic considerations regarding CRP outcome, and we have no data on antibiotics prescribed or CXR result as gold standard." (PMID 33399009, 2020).